CDK4 (cyclin dependent kinase 4)
Diseases named in the same sentence as CDK4 in open-access papers (continued):
Sharing a sentence is not in itself a finding about the gene and the disease.
melanoma (continued). "In melanoma, different pathways are involved, such as the CDKN2A/CDK4 system and pathways involving the extracellular matrix not found in HCL." (PMID 26857260, 2016). "In the present study, 42 Jewish, mainly Ashkenazi, melanoma families with (n=24) or without NST (n=18) were genotyped for germline sequence alterations in the CDKN2A/ARF and CDK4 genes." (PMID 15928671, 2005). "However, the identification of a potentially POT1 PV in a family diagnosed with multiple early-onset melanomas underscores the need for continued genetic screening in hereditary melanoma cases, especially when CDKN2A, CDK4, and BAP1 aberrations are absent." (PMID 40851494, 2025). "Consequently, we performed whole exome sequencing (WES) of 10 probands from 5 different families (2 probands/family) who developed melanoma and had previously tested negative for CDKN2A and CDK4." (PMID 35085295, 2022). "Importantly, as shown in our study, BRAF/MEK/CDK4/6 inhibition produced sustained and durable response in BRAFV600E-mutant melanoma patient-derived preclinical models regardless of drug sensitivity." (PMID 29541385, 2018). "Importantly, MITF depletion in melanoma cells blocked CDK2, p21Cip1 and CDK4 expression even though ERK was not inhibited." (PMID 18628967, 2008). "Furthermore, it reinforces that CDK4, rather than CDK6 (Shennan etal., 2000), is the critical kinase in melanoma." (PMID 18843795, 2008). "However, our investigation demonstrates that CDK4/6 inhibition does not significantly alter the effects of BRAF and MEK inhibitors on either glycolysis or OXPHOS in melanoma cells, nor does it significantly alter the expression of the MITF-PGC1A-mitochondrial metabolism pathway." (PMID 33572972, 2021). "However, an overexpression of KIT and CDK4 has been identified in a subgroup of cutaneous malignant melanomas and would be a mechanism of potential oncogenic transformation of nonmutated BRAF or NRAS melanomas." (PMID 24416617, 2013).
liposarcoma (217 papers, 2000 to 2026). A usually painless malignant tumor that arises from adipose tissue. "Such genetic aberrations are often associated with amplification of oncogenes like MDM2 and CDK4, which are crucial in the development and progression of well-differentiated and dedifferentiated liposarcomas." (PMID 39229483, 2024). "CDK4 and p16 are useful ancillary diagnostic tools to differentiate well-differentiated and dedifferentiated liposarcoma from other adipocytic tumors." (PMID 37016649, 2023). "Expected disease-defining gene alterations were detected in several histological subtypes, including MDM2 and CDK4 in liposarcoma, IDH mutations in chondrosarcoma, and alterations related to tyrosine kinases in GIST (KIT, PDGFR)." (PMID 37542550, 2023). "For example, the most common molecular tests for MDM2 and CDK4 mutations were used to dedifferentiated liposarcoma and undifferentiated pleomorphic sarcoma, and both entities are treated identically." (PMID 35115589, 2022). "Dedifferentiated liposarcomas showed MDM2/CDK4 gene amplifications, as already detected by diagnostic cytogenetics (TOMAS-43, TOMAS-48; both responder patients)." (PMID 36110934, 2022). "The effect of CDK4 amplification on CDK4/6i sensitivity remains controversial; although it enhanced sensitivity in liposarcoma, it caused resistance in glioblastoma." (PMID 35686110, 2022). "CDK4 amplification was present in all but one dedifferentiated liposarcoma, and two potentially targetable mutations of the BRAF/MAPK pathway were detectable in undifferentiated (pleomorphic) sarcomas." (PMID 34356494, 2021). "As we will discuss, the success of CDK4/6 inhibitors in patients with dedifferentiated liposarcoma has validated CDK4 gene amplification as a driver mutation in this subtype and is leading the way for similar trials in additional soft tissue sarcoma subtypes." (PMID 32344731, 2020). "Molecular pathological examination of the MDM2, CDK4 and p16 gene in tumors provides the diagnostic gold standard in distinguishing well-differentiated liposarcoma from lipoma." (PMID 31387607, 2019). "The authors found that co-overexpression of MDM2 and CDK4 causes high-grade sarcoma with a dedifferentiated liposarcoma-like morphology." (PMID 31160689, 2019). "In bone and soft tissue sarcomas, such as osteosarcoma, liposarcoma, rhabdomyosarcoma and chordoma, amplification of CDK4 has been associated with poor prognoses." (PMID 30808351, 2019). "Chest CT scan and MRI can help clarify the diagnosis, and molecular pathological examination of the MDM2, CDK4 and p16 gene in tumors provides the diagnostic gold standard in distinguishing well-differentiated liposarcoma from lipoma." (PMID 31387607, 2019). "Strong staining for MDM2 or CDK4 associates with 12q14‐15 amplification in liposarcoma or well‐differentiated osteosarcoma." (PMID 30667539, 2019). "Amplification and overexpression of MDM2 and CDK4 are well-known diagnostic criteria for well-differentiated liposarcoma (WDLPS)/dedifferentiated liposarcoma (DDLPS)." (PMID 31160689, 2019). "Palbociclib (a CDK4/6 inhibitor) is associated with a favorable progression free rate in RB expressing, CDK4 amplified well-differentiated and de-differentiated liposarcomas that experienced prior progression on systemic treatment." (PMID 27074562, 2016). "Level of CDK4 amplification determined by Q-PCR was associated with the recurrence of WD liposarcomas after surgical resection." (PMID 25121597, 2014).
liposarcoma (continued). "In conclusion, the level of CDK4 amplification determined by Q-PCR was associated with the recurrence of WD liposarcomas of the retroperitoneum and peritoneal cavity." (PMID 25121597, 2014). "Furthermore, the tumor cells were negative for mouse double minute 2 (MDM2) and cyclin-dependent kinase 4 (CDK4), excluding liposarcoma; however, BRG1, BRCA-associated protein 1 (BAP1), integrase interactor 1 (INI1), and histone H3 lysine 27 trimethylation (H3K27ME3) were retained." (PMID 40337377, 2025). "Notably, amplifications of MDM2 and CDK4 are both associated with liposarcoma." (PMID 32722212, 2020). "Nevertheless, Koff and colleagues recently reported that ANGPTL4 contributes to the resistance of liposarcoma cells to CDK4/6 inhibitors, potentially by mitigating senescence features." (PMID 41347893, 2026). "Postoperative pathology combined with fluorescence in situ hybridization (FISH) testing demonstrated MDM2/CDK4 amplification, confirming dedifferentiated liposarcoma (DDLPS)." (PMID 42100410, 2026). "Subtype-specific alterations were observed, including EWSR1 fusions in Ewing sarcoma and CDK4 and MDM2 amplifications in liposarcoma, reflecting well-established pathogenic mechanisms." (PMID 41562936, 2026). "Recent studies in other CDK4-amplified sarcomas, such as dedifferentiated liposarcoma and synovial sarcoma, have demonstrated synergistic antitumor effects and prognostic significance of CDK4/6 inhibition." (PMID 40936693, 2025). "Recent data also highlight CDK4 amplification as a prognostic and therapeutic biomarker in dedifferentiated liposarcoma, offering potential for targeted therapy." (PMID 41303821, 2025). "For instance, dedifferentiated liposarcomas (DLPSs) exhibited amplification of the long arm of chromosome 12 and CDK4/MDM2, which was also observed in corresponding PTCs." (PMID 40054460, 2025). "In high-grade tumor proliferations like dedifferentiated liposarcoma, neoplastic growth is propelled by Rb 1 protein inactivation and mediated by cyclin D-dependent kinases, specifically CDK4 and CDK6." (PMID 40870476, 2025). "These molecular mechanisms have formed the basis for studies investigating the efficacy of selective CDK4/6 inhibitors in patients with liposarcoma." (PMID 40870476, 2025). "These clinical studies have mainly focussed on liposarcoma patients due to CDK4 amplification which is found in nearly all cases." (PMID 40415599, 2025). "Cyclin-dependent kinase 4 (CDK4) amplification occurs in over 90% of well-differentiated and dedifferentiated liposarcomas." (PMID 40075735, 2025). "Based on these results, six patients received targeted therapy: one patient with a CDK4-amplified tumour (dedifferentiated liposarcoma) received CDK4 inhibitor, two patients with angiosarcoma and high TMB received immune checkpoint inhibitor therapy." (PMID 40144205, 2025). "The second most common alteration affected MDM2 and CDK4 genes, this is due to the relative prevalence of dedifferentiated liposarcomas in our cohort." (PMID 40144205, 2025). "Histopathology confirmed well-differentiated liposarcoma (WDLS) with MDM2/CDK4 overexpression and MDM2 amplification via fluorescence in situ hybridization (FISH)." (PMID 40385582, 2025). "MDM2 and CDK4 immunostaining is a helpful adjunct to distinguish dedifferentiated liposarcoma from poorly differentiated sarcomas." (PMID 39297994, 2024). "In well-differentiated and dedifferentiated liposarcomas, cyclin-dependent kinase 4 (CDK4) and MDM2 are overexpressed, providing promising targets for treatment studies." (PMID 39347341, 2024). "Another example is the utilization of ribociclib and everolimus in patients with advanced dedifferentiated liposarcomas, targeting co-amplification of CDK4 and MDM2 genes." (PMID 38730621, 2024). "Lately, novel agents based on MDM2 and CDK4 gene amplifications detected in dedifferentiated and well-differentiated liposarcoma are the subject of numerous ongoing clinical trials." (PMID 39036280, 2024).
liposarcoma (continued). "In contrast, cells were positive for MDM2 and CDK4, suggesting the possibility of a dedifferentiated component in dedifferentiated liposarcoma (DLPS)." (PMID 39602930, 2024). "The histological diagnosis of liposarcoma is considered useful through the detection of protein overexpression due to CDK4 and MDM2 gene amplification." (PMID 38185749, 2024). "Within the female patient, the tumour displayed characteristics of well-differentiated liposarcoma, as evidenced by immunohistochemistry appearing CDK4 partial positivity and changed adipocyte sizes with a few huge nuclei and profoundly stained stromal cells." (PMID 39006714, 2024). "Based on histological morphology, immunohistochemical staining, and MDM2/CDK4 fluorescence in situ hybridization testing, the diagnosis was ovarian mucinous cystadenoma with a mural nodule of well-differentiated liposarcoma." (PMID 39220649, 2024). "Histopathological examination revealed a mass with chondroid metaplasia and limited ossification, with immunohistochemical positivity for MDM2 and CDK4, confirming the diagnosis of a well-differentiated liposarcoma." (PMID 39006714, 2024). "P16, in combination with MDM2 and CDK4, distinguishes atypical lipomatous tumors and dedifferentiated liposarcomas." (PMID 39036280, 2024). "The sensitivity and specificity of MDM2 and CDK4 immunostaining in identifying well-differentiated liposarcoma/dedifferentiated liposarcoma were 97% and 92%, and 83% and 95%, respectively." (PMID 38388450, 2024). "His resected tumour showed biomorphic features with necrotic foci and high murine double minute 2 (MDM2) and CDK4 expression, confirming dedifferentiated liposarcoma (DDLPS)." (PMID 39006714, 2024). "These tumors often exhibit overexpression of CDK4, a characteristic also found in myxoid liposarcomas (MLPS), which is another form of liposarcoma associated with a high likelihood of recurrence and rapid growth." (PMID 38275873, 2024). "When used alone or in combination with CDK4, they significantly reduced tumour growth in liposarcomas with amplified MDM2, as reported in a Phase I clinical trial." (PMID 37681936, 2023). "Since liposarcomas have very high frequencies of CDK4/6 amplification, there have been numerous clinical efforts and trials with CDK4/6 inhibitors." (PMID 36980578, 2023). "A comprehensive NGS approach can also help in the identification of biomarkers associated with disease progression as depicted in case 4BC-63 with liposarcoma that revealed CDK4 and MDM2 amplification." (PMID 36994199, 2023). "Our results showed that CDK4 is a good marker to differentiate benign adipocytic tumors from well-differentiated and dedifferentiated liposarcomas, which was also observed in other studies." (PMID 37016649, 2023). "In adipocytic tumors, the combination of p16 and CDK4 IHC expression can differentiate liposarcomas from benign tumors." (PMID 37016649, 2023). "Palbociclib is a CDK4/6 inhibitor that has shown clinical success for the treatment of both well-differentiated and dedifferentiated liposarcoma in two separate clinical trials." (PMID 36980578, 2023). "The efficacy of CDK4 inhibitors such as palbociclib and abemaciclib in advanced liposarcoma with MDM2/CDK4 amplification is modest in early trials and real-world settings, suggesting a cytostatic rather than cytotoxic effect." (PMID 36652666, 2023). "Seven soft tissue sarcoma cases were submitted, and dedifferentiated liposarcoma was the most frequent pathological diagnosis; therefore, CDK4 and MDM2 amplification were frequently observed among them." (PMID 38067312, 2023). "MDM2 and CDK4 immunohistochemistry display a good application in the diagnosis of liposarcoma and accessory typing." (PMID 37181598, 2023). "In this study, we analyze the immunohistochemical expression of CDK4 and p16 in the various lineages of soft tissue sarcomas and evaluate their role in differentiating atypical lipomatous tumors/well-differentiated liposarcomas from benign lipomas." (PMID 37016649, 2023).
liposarcoma (continued). "When limited to dedifferentiated liposarcoma, interim analysis of a phase II study of abemaciclib, a CDK4/6 inhibitor, in patients with dedifferentiated liposarcoma demonstrated favorable outcomes (30.4 months in median progression-free survival)." (PMID 36003796, 2022). "There have been several studies, including a phase 2 clinical trial in liposarcoma and dedifferentiated liposarcoma, investigating the efficacy of cyclin-dependent kinase 4/6 inhibitors such as palbociclib in the setting of CDKN2A loss." (PMID 35582536, 2022). "MDM2 amplification is a diagnostic criterion for liposarcoma in soft tissue, but at least 80% liposarcomatous differentiation in malignant PT and MC are unassociated with MDM2/CDK4 amplification." (PMID 35814458, 2022). "Several clinical trials investigating the efficacy of CDK4/6 inhibitors for dedifferentiated liposarcoma have been performed or are ongoing." (PMID 36003796, 2022). "In other cases, patients with liposarcoma commonly have genetic alterations tied to the amplification of specific regions on chromosome 12q13-15, which encompasses CDK4 and MDM2." (PMID 36589745, 2022). "Liposarcomas were positive for CDK4 and MDM2 immunohistochemical stains, and the only case tested was found to harbor CDK4 and MDM2 mutations." (PMID 35001360, 2022). "MDM2 and CDK4 amplification can be seen in more than 90% of liposarcoma patients, but the karyotype and gene profile of DDLPS are far more complex than that of WDLPS." (PMID 36531655, 2022). "NGS analyses revealed a very high frequency of CDK4 amplification (88%; 7/8) in the group of dedifferentiated liposarcoma." (PMID 34356494, 2021). "Alteration frequencies differed depending on the sarcoma histotype, e.g., CDK4 amplification in dedifferentiated liposarcomas (DDLS)." (PMID 34356494, 2021). "The immunohistochemical trio of CDK4, MDM2, and p16 is a useful ancillary diagnostic tool that provides strong support for distinguishing differentiated liposarcoma from other adipocytic neoplasms." (PMID 32997268, 2020). "Early phase studies in select soft tissue sarcoma subtypes are showing promising results, particularly for liposarcoma where there is frequent CDK4 amplification." (PMID 32344731, 2020). "The investigation of MDM2 inhibitors has been limited to preclinical and early-phase trials, but there are some phase 2 results for CDK4 inhibitors; liposarcomas showed modest responses to them." (PMID 31963219, 2020). "Among such therapies are CDK4 inhibitors in well- and dedifferentiated liposarcoma (WD/DDLS) and trabectedin, which prevents FUS-DDIT3 binding to DNA, in (M/RCLS)." (PMID 31743843, 2019). "MDM2 and CDK4 overexpression through gene amplification is an early event in liposarcoma tumorigenesis." (PMID 31160689, 2019). "CDK4 amplification with consecutive overexpression has previously been reported in leiomyosarcoma, although, in contrast to liposarcoma, these findings seem less common." (PMID 30804704, 2019). "Simultaneously, combined targeting of MDM2 and CDK4 was synergistic in dedifferentiated liposarcomas." (PMID 31777590, 2019). "The combination of idasanutlin with palbociclib, a highly selective inhibitor of CDK4/6 widely used in clinical trials, was reported to wield great antitumor properties in dedifferentiated liposarcomas when compared to monotherapy." (PMID 31331108, 2019). "A previous study of liposarcoma supports that the overexpression of CDK4 is correlated to a poorer prognosis of patients." (PMID 29670090, 2018).